CXCR3 (C-X-C motif chemokine receptor 3)
Diseases named in the same sentence as CXCR3 in open-access papers (continued):
Sharing a sentence is not in itself a finding about the gene and the disease.
autoimmune disease (continued). "These chemokines can interact with its common receptor CXCR3 to play a vital role in T-cell recruitment and immune response in a number of inflammatory and autoimmune diseases." (PMID 34659199, 2021). "As a group CXCR3 and its ligands have been extensively studied during inflammation and in autoimmune diseases." (PMID 29707158, 2018). "Together these findings indicate that the effects of CXCR3 on the autoimmune diseases were organ specific." (PMID 29868034, 2018). "The chemokine receptor CXCR3 and associated CXC chemokines have been extensively investigated in several inflammatory and autoimmune diseases as well as in tumor development." (PMID 30210493, 2018). "In the current study, we took advantage of this mice to explore the roles of CXCR3 in the autoimmune diseases of different organs by examining the effects of deleting this gene on the infiltrating T cells and disease severity in the liver and colon." (PMID 29868034, 2018). "Our findings provide new insights to the CXCR3-related mechanisms for organ-specific autoimmune diseases." (PMID 29868034, 2018). "In this context, the association between aab targeting CXCR3 and CXCR4 remained stable despite the presence of autoimmune diseases." (PMID 30523250, 2018). "Widespread autoimmune diseases such as systemic lupus erythematosus [SLE] can also have skin-related manifestations that involve CXCR3 and its ligands." (PMID 30320116, 2018). "In contrast, during inflammatory and autoimmune disease inhibition of CXCR3 and its ligands reduces the activated T cells and enhances Tregs in peripheral inflammatory sites to mitigate inflammation by reducing inflammatory cytokines." (PMID 29707158, 2018). "CXCR3 modulated the functions of T cells involved in different autoimmune diseases, whereas the consequence of such modulation was organ-specific regarding to their effects on disease severity." (PMID 29868034, 2018). "We also showed that deletion of a single factor CXCR3 resulted in opposite outcomes to the autoimmune diseases in different organs." (PMID 29868034, 2018). "Increased expression of CXCL10 and CXCR3 was shown in various autoimmune diseases, and they play fundamental parts in leukocyte homing into the inflamed tissues to accelerate the process of tissue damage." (PMID 29456788, 2017). "Binding of CXCL10 chemokines and CXCR3 plays a vital role in Th immune response, which is responsible for organ-specific autoimmune diseases." (PMID 29383139, 2017). "This is the case of CXCR3 and CCR6, which are associated with the recruitment of pathological Th1; Th17 and Th17.1 in various inflammatory and autoimmune disorders." (PMID 28873441, 2017). "CXCR3 and its ligands are involved in the pathogenesis of infection, autoimmune diseases, acute allograft rejection, and tumor growth." (PMID 26475448, 2016). "The accumulated data suggest a critical role of the CXCR3/chemokine system in the development of autoimmune disorders." (PMID 26150899, 2015). "This would suggest some similarity between SPTL and EN regarding the CXCR3 pathway involved in the development of autoimmune diseases." (PMID 25928531, 2014). "To conclude, markers of CXCR3 pathway, typically involved in autoimmune diseases, were expressed both in SPTL and in control (LEP and EN) cases, but in SPTL, the main source of CXCL9 and CXCR3-positive cells was the malignant, CD8+ lymphocyte infiltrate." (PMID 25928531, 2014). "Both CCR6 and CXCR3 play an important role in the recruitment of CD4+ T cells in many autoimmune diseases." (PMID 24223818, 2013). "In many Th-1-dominant autoimmune disorders, it has previously been determined that IP-10 and its receptor, CXCR3, play a role both in leukocyte recruitment to inflamed tissue and in the process of tissue damage." (PMID 24499523, 2013). "Further, CXCR3- and Th1-dependent host responses have been observed in many models of autoimmune diseases." (PMID 24278169, 2013).
autoimmune disease (continued). "The effects of CXCR3 blockade in autoimmune diseases are therefore probably mediated through inhibition of Th1 lymphocyte trafficking to sites of chronic inflammation." (PMID 22992408, 2012). "In the last few years, strong experimental and clinical evidence has been obtained supporting the idea that the CXCR3 pathway is involved in the development of autoimmune diseases, thereby inducing worsening of clinical manifestations." (PMID 21647407, 2011). "CXCR3 antagonists can block the binding of CXCR3 to its ligands, thereby inhibiting the biological signaling axis, which may offer therapeutic benefits for conditions such as tumors and autoimmune diseases." (PMID 40786052, 2025). "CXCR3 antagonists were initially proposed for the treatment of inflammatory and autoimmune diseases; however, recent studies suggest that they may have therapeutic potential in a broader spectrum of diseases." (PMID 40786052, 2025). "CXCR3 not only plays a key role in the development and metastasis of various tumors, but it is also critically involved in the pathogenesis of inflammatory responses and autoimmune diseases." (PMID 40786052, 2025). "CXCR3 antagonists were also devoted to inflammatory and autoimmune diseases." (PMID 38177682, 2024). "CXCR3, mostly expressed on the surface of activated T cells, B cells, and natural killer cells, plays a crucial role in infection, autoimmune diseases, and tumor immunity by binding to specific receptors on target cell membranes to induce targeted cell migration and resulting immune responses." (PMID 37834457, 2023). "CXCR3 knockout mice are reported to be more resistant to autoimmune diseases." (PMID 37834457, 2023). "Interestingly, the chemokine CXCL10, a ligand of CXCR3, was detected and appear to contribute to the pathogenesis of various autoimmune disease." (PMID 36591302, 2022). "IRBP interacts with chemokine receptors CXCR5 and CXCR3, and arrestin interacts with CXCR3, and both the proteins can facilitate retinal damage by inflammatory and immune responses, and potentially contribute to the development of autoimmune diseases, such as autoimmune uveitis." (PMID 34926479, 2021). "As CD40L and CXCR3 are strongly associated with the autoimmune disorder systemic lupus erythematosus (SLE), this inspired further work to characterise potential links between XIST localisation and the autoimmune disease." (PMID 31336952, 2019). "However, during autoimmune diseases and infection by Leishmania major, CXCR3 is important for cytokine production and proliferation by CD8+ T-cells." (PMID 31356587, 2019). "Our results provide new information for the function of CXCR3 in autoimmune diseases." (PMID 29868034, 2018). "Our findings emphasize the importance of extra caution in immunotherapy for organ-specific autoimmune diseases, as therapeutic interventions aiming at a target such as CXCR3 for certain disease could result in adverse effects in an unrelated organ." (PMID 29868034, 2018). "Given the association between the CXCR3 system and inflammation, it is perhaps not surprising that CXCR3 and its ligands also play a role in a variety of autoimmune diseases." (PMID 30320116, 2018). "Previous works have focused on the chemotaxis function of CXCR3 in autoimmune diseases and cancer." (PMID 29868034, 2018). "CXCR3 pathway is involved in the development of autoimmune diseases." (PMID 25866451, 2015). "CXCR3 is an important regulator of natural killer (NK) lymphocyte, NK T lymphocyte and T-helper type 1 (Th1) lymphocyte trafficking in response to viral infection, allotransplantation, cancer and autoimmune diseases." (PMID 22992408, 2012). "Therefore, exploring combination therapies involving CXCR3 antagonists and other drugs may enhance therapeutic efficacy, particularly in the treatment of tumors and autoimmune diseases." (PMID 40786052, 2025).
autoimmune disease (continued). "Several small-molecule inhibitors of CXCR3 have been tested in experimental studies, with AMG487 being clinically trialed for treatment of inflammatory and autoimmune diseases." (PMID 39109081, 2024). "Due to the indispensable role of CXCR3 in TH1-type inflammation, extensive studies of CXCR3 were conducted in infection, autoimmune diseases, transplantation and cancers." (PMID 38177682, 2024). "Inflammation of the skin resulting from infections or autoimmune disease drives expression of CXCL9/10/11 and the subsequent recruitment of effector, CXCR3+ T cells from the circulation." (PMID 30320116, 2018). "CXCR3 blockage usually results in attenuation of inflammation due to decreased infiltration of autoreactive CD4+ T cells and CD8+ T cells in autoimmune diseases." (PMID 29868034, 2018). "Accordingly, it may be important to consider the use of anti-CXCR3 and anti-CXCL10 treatments, both of which are now being used in the clinical setting for attenuating autoimmune disease." (PMID 41273416, 2026). "Many CXCR3 antagonists have been developed to treat autoimmune diseases, but none have yet been FDA-approved." (PMID 39000234, 2024). "In particular, the role of CXCR3 in different autoimmune diseases has not been fully elucidated, due to the complexity of its functions and different effects of CXCR3 on various diseases." (PMID 29868034, 2018). "In an inflammatory condition CXCR3 is highly expressed at peripheral inflammatory sites and global inhibition of CXCR3 therapeutically in human autoimmune disease is not giving predicted results." (PMID 29707158, 2018). "In conclusion, we have taken advantage of the CD25−/− mouse model of autoimmune diseases in two distinct organs to reveal new regulatory effects of the CXCR3 pathway that does not involve its chemotaxis function." (PMID 29868034, 2018). "More relevant to the mechanism of autoimmune disease, our results also support the notion that the pathology results from the upregulation of CXCR3 on effector cells, rather than on specific cytokine profiles." (PMID 27624792, 2016). "Among them, CXCR3 and its chemokines CXCL10, CXCL9, and CXCL11 are widely involved in the pathogenesis of autoimmune diseases such as HT, GD, thyroid eye disease (TED), type 1 diabetes, and autoimmune Addison’s disease, and may be potential targets for new drugs to treat these diseases." (PMID 35720300, 2022). "Therefore, we propose that dual targeting of CXCR3 and CCR6 with a fully humanized BsAb may display a potent interventional approach for the treatment of inflammatory and autoimmune diseases." (PMID 28873441, 2017). "Recent reports have shown that serum and/or tissue expressions of CXCR3 and CXCL10 are increased in various autoimmune diseases, which may have important roles in leukocyte homing to inflamed tissues and in the perpetuation of inflammation, and therefore, tissue damage." (PMID 21647407, 2011). "However, it was not clear whether the effects of CXCR3 in these two autoimmune diseases were mediated by its chemotaxis function, or by its other immune regulatory function." (PMID 29868034, 2018).
influenza (59 papers, 2012 to 2025). An acute viral infection of the respiratory tract, occurring in isolated cases, in epidemics, or in pandemics; it is caused by serologically different strains of viruses (influenzaviruses) designated A, B, and C, has a 3-day incubation period, and usually lasts for 3 to 10 days. "A recent report suggested that blocking CXCR3 may also alleviate T cell–driven pulmonary pathology caused by influenza infection." (PMID 39565860, 2024). "Murine NK cells are recruited to the lungs in response to influenza in a CXCR3- and CCR5-dependent manner." (PMID 38684766, 2024). "Human NK cells, including CXCR3 + NK cells, accumulate in the lungs of individuals with acute influenza infection and exhibit a hyperresponsive phenotype." (PMID 38684766, 2024). "In influenza infection, CXCR3 is important for promoting T follicular helper (TFH) cell activity and antibody production, and in mouse TB models it is a marker for a protective antigen-specific CD4+ T cell subset." (PMID 37896952, 2023). "In particular, cTfh cells expressing CXCR3 are important in the response to influenza vaccine, inducing a strong antigen-specific antibody response." (PMID 35710943, 2022). "The activation of CXCR3 by CXCL10 triggers influenza-induced neutrophil infiltration, and the deletion of CXCL10 and CXCR3 results in increased survival." (PMID 35601109, 2022). "In other respiratory viral diseases such as influenza, CXCR3+ TFH cells were shown to correlate positively with the development of protective antibody responses." (PMID 34113347, 2021). "For example, virus-specific cytotoxic T lymphocytes (CTLs) are quickly recruited to influenza-infected lungs by a Th1 response, specifically due to the production of IFNγ Two of these Th1-type effector T-cell chemokine receptors are CXCR3 and CX3CR1." (PMID 34394127, 2021). "A previous study showed that CXCR3 is expressed on lung-recruited neutrophils during influenza pneumonia." (PMID 33986193, 2021). "Within 3 days following low dose influenza infection in mice, CXCR3+ and CCR5+ NK cells accumulate in the lung, airways, and lung-draining lymph nodes." (PMID 32974217, 2020). "In the case of CXCR3 we saw strong signals amongst the influenza-specific T cells in some subjects, but generally only few of the citrulline-specific T cells were CXCR3+." (PMID 32423478, 2020). "Strikingly, hybrid Th1/Tfh cells (ICOS+CXCR3+CXCR5+) did correlate with antibody levels in influenza, where they were also shown to contain IFN-γ+IL-21+ T cells." (PMID 32634740, 2020). "This difference in mRNA was also reflected at the protein level, with the proportion of CXCR3+ cTfh cells increasing after influenza vaccination and a reciprocal decrease in CCR6+ cTfh cells." (PMID 31175140, 2019). "Similar increases in blood CXCR3+CXCR5+ICOS+ Tfh cells occurred 7 days after influenza vaccination and correlated with anti-influenza antibody and plasmablast production." (PMID 29904381, 2018). "To this end, we analyzed IL-4 production by both CXCR3− and CXCR3+ NKT cell groups on day 3 of influenza infection by flow cytometry and enzyme-linked immunospot (ELISPOT)." (PMID 29249358, 2018). "By comparison, data reported here is consistent with other results that show that the CXCR3+ cTFH subset responds to immediate antigenic challenge, particularly after influenza vaccination." (PMID 30303980, 2018). "A subset of circulating ICOS+CXCR3+CXCR5+ TFH cells was reported to play a crucial part in inducing antibody responses in seasonal influenza vaccine trials." (PMID 28533093, 2017). "The Th1-polarized CXCR3+ cTfh cell subset specifically has been shown to correlate with high-avidity antibodies 7 days after influenza vaccination in humans." (PMID 29181005, 2017). "Studies have shown that CXCR3+ cTfh cells correlate with high-avidity antibodies against influenza after vaccination in humans." (PMID 29181005, 2017).
influenza (continued). "Generation of ICOS+PD-1+CXCR3+ Tfh cells is important for the generation of protective antibody response in influenza vaccine, in particular for subjects who have few highly cross-reactive antigen-experienced B cells." (PMID 27231124, 2016). "These chemokines bind to CXCR3, signaling mediated by which has been revealed in the pathogenesis of influenza." (PMID 26008703, 2015). "These three chemokines bind to a common receptor CXCR3, and the importance of CXCR3 signaling has been shown in the pathogenesis of several viruses including influenza." (PMID 22396727, 2012). "Indeed, blocking CXCR3-mediated trafficking during influenza infection in mice resulted in an accumulation of influenza-specific CD4+ T cells in the T-cell zone and an impaired B-cell response." (PMID 39932316, 2025). "Indeed, recent studies showed that persistent CXCR3-driven recruitment of cytotoxic CD8 T cells to the lung following the resolution of active infection promoted lung injury in a mouse model of severe influenza." (PMID 41285788, 2025). "In the influenza compartment, we observed an increased signal for Th1 (CXCR3+CCR6−) cells." (PMID 39557489, 2024). "Thus, IL-4C enhanced the migration of both antigen-specific and bystander CD8 T cells into inflamed lungs after influenza infection by triggering antigen-independent upregulation of CXCR3 expression in CD8 T cells." (PMID 38037190, 2023). "In prior studies, antigen-specific ICOS+CD38+ cTfh expressed CXCR3 following influenza vaccination." (PMID 34874183, 2022). "The expression levels of the main surface markers characterizing peripheral Tfh and Th1 cells (i.e. CXCR5, PD-1 and CXCR3) are shown on HCV-specific CD4 T cells in comparison to influenza- (Flu-) specific CD4 T cells ex vivo in a representative HCV-infected, DAA-cured or healthy donor, respectively." (PMID 34659236, 2021). "Similarly, a recent study showed that emergence of plasmablasts and ICOS+CXCR3+CXCR5+CD4+ T cells in blood peaked on day 7 after influenza vaccination." (PMID 30055570, 2018). "Interestingly, flow cytometry analysis of lymph nodes from influenza-infected mice revealed that 80% of IL-4 GFP+ NKT cells express CXCR3, whereas only 30% of IL-4 GFP− NKT cells express this marker." (PMID 29249358, 2018). "Germinal centers were formed in vaccine-draining lymph nodes along with an increase in circulating H10-specific ICOS+ PD-1+ CXCR3+ T follicular helper cells, a population shown to correlate with high avidity antibody responses after seasonal influenza vaccination in humans." (PMID 29181005, 2017). "However, in response to influenza vaccine, CXCR3+ Tfh1-like cells transiently expressed ICOS, along with PD1, which peaked on day 7 post-vaccination, and that these cells were able to provide help to memory B cells." (PMID 26333070, 2015). "Notably, CXCR3 blockade during late-stage CD8 T cell responses in influenza-cleared lungs can mitigate lung injury without affecting viral clearance, suggesting therapeutic potential for preventing influenza-associated lung injury." (PMID 40552264, 2025). "In addition, a study that observed CXCR3+ cTfh to positively correlate with antibody responses after influenza vaccination also showed that CXCR3+ Tfh that were localized to tonsillar GCs, expressed Fas-L, secreted IFNγ, lacked CD154 expression, and suppressed the activity of GC B cells." (PMID 30090099, 2018). "Thus, even in the influenza system, IL-12 probably indirectly downregulates CXCR3." (PMID 26244629, 2015). "Overall, dynamics of the three cTFH cell subpopulations (cTFH1 [CD3+CD4+CXCR5+CXCR3+CCR6−], cTFH2 [CD3+CD4+CXCR5+CXCR3−CCR6−], and cTFH17 [CD3+CD4+CXCR5+CXCR3−CCR6+]) differed after influenza vaccination." (PMID 36705404, 2023). "In vivo administration of IL-4 and an anti-IL-4 antibody complex (IL-4C) increased CXCR3 expression in both memory and naïve phenotype CD8 T cells in the absence of antigenic stimulation, and protected mice from lethal influenza infection." (PMID 38037190, 2023).